SPDYE18 (speedy/RINGO cell cycle regulator family member E18)
Tractability: No criterion of Open Targets' tractability assessment is met for any kind of drug.
Gene: Protein-coding gene on chromosome 7 (77,050,391 to 77,063,938, reverse strand). Ensembl gene ENSG00000205482.
Gene Ontology:
Molecular function: protein kinase binding
Genetic constraint (gnomAD): Loss-of-function variants: 6 observed, 21.01 expected, observed/expected ratio (o/e) 0.29, 90% interval 0.16 to 0.56. The synonymous counts are far from expectation, so gnomAD's model fits this gene poorly and the ratio says little. Missense variants: 118 observed, 224.67 expected, observed/expected ratio (o/e) 0.53, 90% interval 0.45 to 0.61. Synonymous variants: 34 observed, 83.8 expected, observed/expected ratio (o/e) 0.41, 90% interval 0.31 to 0.54.
Homologues: Orthologues: mouse Spdye4a (38% identical), rat Spdye4 (38% identical), mouse Spdye4b (34% identical). Paralogues in human: SPDYE16 (98% identical), SPDYE21 (95% identical), SPDYE2 (94% identical), SPDYE2B (93% identical), SPDYE5 (93% identical), SPDYE6 (93% identical), SPDYE1 (92% identical), SPDYE3 (72% identical), SPDYE12 (63% identical), SPDYE13 (63% identical), SPDYE14 (63% identical), SPDYE15 (63% identical), and 6 more.